CDK11B (cyclin dependent kinase 11B)
Description:
Cyclin-dependent protein kinase that acts as a regulator of transcription and pre-mRNA splicing. Acts as a key regulator of pre-mRNA splicing by mediating phosphorylation of SF3B1, enabling the association between SF3B1 and U5 and U6 snRNAs in the activated spliceosome, thereby promoting spliceosome assembly. Also acts as a regulator of transcription by phosphorylating 'Ser-2' of the CTD (C-terminal domain) of the large subunit of RNA polymerase II (RNAP II) POLR2A. Involved in replication-dependent transcription of histone genes: binds to histone genes and phosphorylates POLR2A at 'Ser-2' of the CTD to specifically control transcriptional elongation of histones and recruitment of 3'-end processing factors. Part of a transcription checkpoint upstream of CDK9, which regulates promoter-proximal pausing by RNA polymerase II, a transcription halt following transcription initiation, but prior to elongation. Probably regulates promoter-proximal pausing by mediating phosphorylation of POLR2A at 'Ser-2' of the CTD. Activated by the CDK-activating kinase (CAK) complex consisting of CDK7, cyclin-H/CCNH and MAT1, which is a master regulator of CDK activity. [Isoform SV9]: Isoform expressed in a non-cell cycle-dependent manner. [Isoform 7]: Isoform specifically expressed during the G2-M phases of the cell cycle. Phosphorylates 'Ser-2' of the CTD (C-terminal domain) of the large subunit of RNA polymerase II (RNAP II) POLR2A. Promotes centromeric transcription to maintain centromeric cohesion during mitosis.
Synonyms: CLK-1; CDC2L1; CDK11; PITSLREA; CDK11-p110; CDK11-p58; CDK11-p46; PK58; p58; p58CDC2L1; p58CLK-1
Tractability: Small molecule: a drug acting on it is in phase 2 or 3 trials; a structure with a bound ligand is known; a high-quality ligand is known; it belongs to a druggable protein family. PROTAC: it is named in the literature on targeted protein degradation; UniProt records ubiquitination sites on it; ubiquitination databases record sites on it; its protein half-life has been measured; a small molecule that binds it is known.
Target class: Kinase; Enzyme; Protein Kinase; CMGC protein kinase PITSLRE subfamily; CMGC protein kinase group; CMGC protein kinase CDK family
Gene: Protein-coding gene on chromosome 1 (1,635,225 to 1,659,234, reverse strand). Ensembl gene ENSG00000248333.
Subcellular location: Nucleus; Chromosome; Cytoplasm; Nucleus (Isoform SV9); Nucleus (Isoform 7); Chromosome, centromere
Subcellular location (Human Protein Atlas): Nuclear speckles
Pathways (Reactome):
Cell Cycle: Recruitment of mitotic centrosome proteins and complexes
Gene Ontology:
Molecular function: ATP binding; cyclin-dependent protein serine/threonine kinase activity; protein binding; protein serine kinase activity; protein serine/threonine kinase activity; RNA binding; RNA polymerase II CTD heptapeptide repeat kinase activity; RNA polymerase II CTD heptapeptide repeat S2 kinase activity; RNA polymerase II CTD heptapeptide repeat S5 kinase activity; protein kinase activity
Biological process: mitotic sister chromatid cohesion, centromeric; protein phosphorylation; regulation of cell growth; regulation of mRNA processing; regulation of mRNA splicing, via spliceosome; RNA polymerase II promoter clearance; apoptotic process; mitotic cell cycle; regulation of DNA-templated transcription; regulation of cell cycle; regulation of transcription by RNA polymerase II
Cellular component: chromosome; cyclin L-CDK11 complex; cyclin-dependent protein kinase holoenzyme complex; nuclear speck; nucleus; cytoplasm; chromosome, centromeric region
Genetic constraint (gnomAD): Loss-of-function variants: 28 observed, 42.54 expected, observed/expected ratio (o/e) 0.66, 90% interval 0.49 to 0.9. The upper end of that interval is the gene's LOEUF score, 0.9, which puts it in group 3 of 6, group 1 being the genes least tolerant of losing a copy. Missense variants: 313 observed, 459.46 expected, observed/expected ratio (o/e) 0.68, 90% interval 0.62 to 0.75. Synonymous variants: 217 observed, 181.67 expected, observed/expected ratio (o/e) 1.19, 90% interval 1.07 to 1.34.
Homologues: Orthologues: chimpanzee CDK11 (99% identical), macaque CDK11B (99% identical), rat Cdk11b (97% identical), mouse Cdk11b (97% identical), dog CDK11 (92% identical), rat AABR07040938.1 (86% identical), tropical clawed frog cdk11b (83% identical), zebrafish cdk11b (79% identical), Drosophila melanogaster Pitslre (49% identical). Paralogues in human: CDK11A (98% identical), CDK13 (24% identical), CDK12 (24% identical), CDK17 (24% identical), CDK10 (23% identical), CDK16 (22% identical), CDK14 (21% identical), CDK18 (21% identical), CDK15 (19% identical), PRP4K (19% identical), CDK7 (18% identical), CDK2 (18% identical), and 14 more.
Diseases named in the same sentence as CDK11B in open-access papers:
CDK11B is named in the same sentence as 11 diseases in open-access papers, as found by Europe PMC text mining. Sharing a sentence is not in itself a finding about the gene and the disease. The quoted sentences say what the papers report.
neuroblastoma (3 papers, 2015 to 2021). Neuroblastoma (NB) is the most common solid, extracranial childhood tumor. "CDK11B has been shown to be involved in neuroblastoma while MAP4K5 has been suggested to have a role in stress response." (PMID 33845866, 2021). "Two CDK family genes, CDK11A and CDK11B, are known to play multiple roles in cell cycle progression, cytokinesis and apoptosis, while the gene NBPF1 acts as a tumor suppressor by arresting cell cycle at G1 stage in Neuroblastoma." (PMID 29621297, 2018).
hepatocellular carcinoma (2 papers, 2021 to 2025). A malignant tumor that arises from hepatocytes. "USP22 promotes the proliferation of hepatocellular carcinoma cells by stabilising CDK11B and enhances resistance to Sorafenib by inhibiting ferroptosis through the USP22/H2BK120ub/TFRC axis." (PMID 40341781, 2025). "Taken together, this study demonstrates that USP22 promotes hepatocellular carcinoma growth and inhibits Sorafenib‐induced ferroptosis by deubiquitinating non‐histone substrate CDK11B and histone H2B, respectively." (PMID 40341781, 2025). "To establish the relationship between the promotion of cell proliferation and the stabilisation of CDK11B protein caused by USP22 overexpression, we intended to first examine the effects of CDK11B knockdown on hepatocellular carcinoma cell proliferation." (PMID 40341781, 2025). "In this study, we demonstrate that USP22 promotes the proliferation of hepatocellular carcinoma cells by stabilising cyclin‐dependent kinase 11B (CDK11B)." (PMID 40341781, 2025). "In summary, our study demonstrated that USP22 promotes the growth of hepatocellular carcinoma and resistance to Sorafenib‐induced ferroptosis by removing ubiquitin moieties from non‐histone protein CDK11B and histone H2B." (PMID 40341781, 2025). "Taken together, these results indicated that USP22 interacts with CDK11B in hepatocellular carcinoma cells." (PMID 40341781, 2025). "USP22 promotes the proliferation of hepatocellular carcinoma cells via deubiquitinating and stabilising cyclin‐dependent kinase CDK11B, and it inhibits Sorafenib‐induced ferroptosis by decreasing H2BK120ub occupancy at TFRC TSS downstream region." (PMID 40341781, 2025). "Our data further indicates that USP22 promotes the proliferation of hepatocellular carcinoma cells via deubiquitinating and stabilizing cyclin‐dependent kinase 11B (CDK11B)." (PMID 40341781, 2025). "To further validate that USP22 increases hepatocellular carcinoma cell proliferation by stabilising CDK11B protein, we overexpressed His‐CDK11B in USP22 knockout cells and evaluated cell proliferation." (PMID 40341781, 2025). "Moreover, immunofluorescent staining was conducted, revealing the co‐localisation of USP22 and CDK11B in hepatocellular carcinoma cells." (PMID 40341781, 2025). "The results manifested that USP22 interacts with CDK11B in hepatocellular carcinoma cells." (PMID 40341781, 2025).
liver fibrosis (1 paper, 2025). "Our study further validated the aberrant activation of STK4 (serine/threonine-protein kinase 4), GSK3α (glycogen synthase kinase 3α), and CDK11B (cyclin-dependent kinase 11B) in liver fibrosis mice and found that their small-molecule inhibitors have antihepatic fibrosis effects." (PMID 40368138, 2025). "•Three dysregulated kinases, STK4, GSK3α, and CDK11B, were screened out in mouse liver fibrosis." (PMID 40368138, 2025).
melanoma (1 paper, 2019). A malignant, usually aggressive tumor composed of atypical, neoplastic melanocytes. "Gene mutation is not a major component of CDK11A, CDK11B, CCNL1 or CCNL2 function in melanoma." (PMID 30987032, 2019). "It is not surprising that the genes CDK11A and CDK11B and CCNL2, which are all located on chromosome 1p, showed good correlation of expression at the mRNA level in melanoma patient tumor tissues." (PMID 30987032, 2019).
osteosarcoma (1 paper, 2020). A usually aggressive malignant bone-forming mesenchymal neoplasm, predominantly affecting adolescents and young adults. "This study revealed the CDK11B role in cancer pathogenesis and proposed its targeting as a potential approach in augmenting osteosarcoma patients’ survival." (PMID 33117331, 2020).
tumor (7 papers, 2015 to 2025). "Consistent with the results at the cellular level, the protein level of CDK11B was reduced in USP22 knockout tumour tissues compared to the control group." (PMID 40341781, 2025). "By examining the mutated genes, we found that tumor cells progressively acquired non-synonymous mutations in genes such as KTN1, ALB, APOB, CDK11A, and CDK11B." (PMID 41373592, 2025).
cancer (4 papers, 2015 to 2025). A tumor composed of atypical neoplastic, often pleomorphic cells that invade other tissues. "CDK11B, characterized by an in-frame insertion in the proband, was known to likely be linked to predisposition to various human cancers." (PMID 34573430, 2021). "Many synthetic lethalities involved CDK proteins that had yet to be investigated as anti-cancer drug targets, such as the transcriptional regulators CDK11B and CDK15." (PMID 37169829, 2023). "CDK11B and its homologue gene encoding CDK11, a protein kinase that has been shown to be involved in the proliferation of various cancer cells, is involved in modulating the Wnt/β-catenin pathway in colon cancer." (PMID 34573430, 2021).
CDK11B also shares sentences with these, for which no sentence is quoted: breast carcinoma (2 papers); breast tumor (1); immune dysfunction (1); intellectual disabilities (1).